CCR2 (C-C motif chemokine receptor 2)
Diseases named in the same sentence as CCR2 in open-access papers (continued):
Sharing a sentence is not in itself a finding about the gene and the disease.
monocytopenia (11 papers, 2012 to 2024). "Analysis of blood from iCCR-deficient and CCR2-deficient mice demonstrated equivalent Ly6Chi monocytopenia (70%–80%) to that seen in resting mice." (PMID 30784579, 2019). "As expected, our results showed that CCR2 deficiency in the hematopoietic system resulted in an important blood monocytopenia." (PMID 27930721, 2016). "It is important to note that CCR2-deficient mice are characterised by a profound monocytopenia, and thus, aspects of the phenotypes observed in adult CCR2-deficient mice may be explained by the general reduction in myelomonocytic cells." (PMID 25271254, 2014). "Ccr2-/- mice exhibit constitutive monocytopenia throughout their lives, whereas CCR2-DTR mice only undergo acute monocytic depletion." (PMID 39418302, 2024). "For the first time we demonstrated that 6-month-old APPSwe/PS1 mice exhibited in the bloodstream a significant reduction of monocyte frequency, resulting of monocytopenia in the CX3CR1lowLy6-ChighGr1+CCR2+ subset." (PMID 23125823, 2012). "Additionally, monocytopenia is also present in AD patients and CCR2, a critical receptor expressed by Ly6Chigh monocytes, is shown to be decreased in monocytes of AD patients." (PMID 36388139, 2022). "One other interesting feature of this resting tissue analysis is that, despite a profound monocytopenia in CCR2-deficient mice, there was no statistical difference in the numbers of Ly6Chi cells in resting skin between these mice and WT mice." (PMID 30784579, 2019). "Fifth, the robust inhibition of monocyte infiltration in the neuron-specific CCL2-deficient mice argues explicitly that this chemokine drives trafficking to the brain while side-stepping all of the issues regarding monocytopenia that arise in CCL2−/− or CCR2−/− mice." (PMID 29202854, 2017). "Similar to our results, monocytopenia was observed in blood of CCR2-/- mice infected with WNV." (PMID 27930721, 2016). "However, when we analyzed the levels of CM in the spleen of Ccr2–/– recipients, we found monocytopenia, which could potentially explain the reduction in the CM recruitment to the lung allograft in these recipients." (PMID 33621212, 2021). "Thus, the lack of inflammatory monocytes recruitment observed in the CNS of mice having a peripheral deficiency may either be due to the monocytopenia or the absence of CCR2-dependent monocytes trafficking from the blood to the brain." (PMID 27930721, 2016). "Overall, our data suggest that mice carrying a hematopoietic deficiency in CCR2 may not be able to overcome monocytopenia during HSV-1 infection and that the lack of this receptor affects particularly the recruitment of inflammatory monocytes, which appears to be needed for the control of HSE." (PMID 27930721, 2016). "However, the ability of the pharmacological blocker of CCR2 to inhibit post-inflammation vessel regeneration again suggests that the phenotype observed is not simply related to monocytopenia but to reduced macrophage recruitment directly to the vicinity of developing/regenerating vessels." (PMID 25271254, 2014).
multiple myeloma (11 papers, 2003 to 2025). "We have previously showed that the multiple myeloma cell line U266 expressed CCR2 and is susceptible to GMME1-induced apoptosis." (PMID 21943176, 2011). "Furthermore, the bone lesion number in patients with newly diagnosed MM was associated with high CCR2 expression in myeloma plasma cells." (PMID 36212502, 2022). "In a mouse model of multiple myeloma, osteoclasts have been found to express CCR2-targeting chemokines, and an anti-CCR2 monoclonal antibody was able to block osteoclast chemoattractant activity for multiple myeloma cells." (PMID 34804061, 2021). "The fact that GMME1 protein can significantly induce cell death of CCR2+ primary myeloma from patients indicates its potential clinical utility." (PMID 21943176, 2011). "Profiling of CD38+CD138+CD45- myeloma cells isolated from patients by FACS confirmed the expression of the chemokine receptor CCR2." (PMID 21943176, 2011). "Specifically, the expression of this chemokine receptor, in addition to CCR1 and CCR2, is correlated with disease state and survival in myeloma patients." (PMID 21375780, 2011). "For example, the expression of CXCR4 is associated with R-ISS staging and the prognosis of MM, and the expression of the SOX2 protein and the chemotaxis-related genes CCR1, CCR2, and MCP-1 affect the biological properties of myeloma cells." (PMID 41416066, 2025). "In light of this inter-species permissiveness, we assessed the pharmacological properties of mouse GMME1 on the human multiple myeloma cell line U266, a CD19-/- human myeloma cell line shown to express the plasma cell marker CD138 and CCR2." (PMID 21943176, 2011). "We tested the effect of GMME1 on the CCR2-expressing murine EG7 lymphoid and the human U266 myeloma cell lines in vitro." (PMID 21943176, 2011). "In this study, we report that primary MM cells and myeloma derived cell lines (Karpas, LP-1 and MM5.1) express the chemokine receptor CCR2." (PMID 12644822, 2003). "We present two examples – one of CCR2/CD192, a chemokine receptor expressed on monocytes, and CD38, a glycoprotein expressed on the surface of multiple immune cell types, and a target of therapies for multiple myeloma." (PMID 33835024, 2021). "Importantly, in vitro experiments showed that an anti-CCR2 MoAb blocked osteoclast chemoattractant activity for myeloma cells, but it did not inhibit osteoclast MM cell growth activity." (PMID 36212502, 2022). "Thus, the overexpression of FGFR1, CCR2, and SGK1 may explain the low sensitivity of multiple myeloma (MM) cells to bortezomib and ixazomib." (PMID 33406639, 2021). "However, reduced expression of cell adhesion molecules like VLA-4, CD44, P-selectin, and CD56, promotion of homing of myeloma cells by decreased expression of chemokine receptors like CCR1, CCR2, and CXCR4, and increased angiogenesis have been proposed as mechanisms." (PMID 31467739, 2019).
osteosarcoma (11 papers, 2008 to 2025). A usually aggressive malignant bone-forming mesenchymal neoplasm, predominantly affecting adolescents and young adults. "The axis of CCL2/CCR2-mediated monocyte recruitment and polarization to M2-like TAMs has been causally linked to metastatic seeding in osteosarcoma models, a finding consistent with our inference of enhanced monocyte-to-macrophage differentiation within tumors." (PMID 41346635, 2025). "A previous study suggested that TIPE1 suppresses osteosarcoma cancer cell growth by inhibiting MCP-1 expression in osteosarcoma cells, thus inhibiting the MCP-1/CCR2 axis via macrophage-osteosarcoma cell crosstalk." (PMID 36151091, 2022). "However, the present study suggested that AP-1 played a crucial role in MCP-1/CCR2-directed metastasis in osteosarcoma." (PMID 33228783, 2020). "In addition to the CCR2 inhibitor and mAb, we used CCR2 siRNA to confirm the involvement of CCR2 in MCP-1-promoted osteosarcoma cell migration." (PMID 33228783, 2020). "A study of 27 patient samples with osteosarcoma revealed CCR2 expression in every sample." (PMID 33228783, 2020). "In this study, CCR2 instead of CCR4 was involved in osteosarcoma migration in vitro." (PMID 33228783, 2020). "As a CCL2 receptor, the expression of CCR2 was detected in 100% of the 27 osteosarcoma samples." (PMID 25695619, 2015). "Consequently, we examined whether MCP-1 induced MG63 osteosarcoma cell migration through the CCR2 or CCR4 receptor by using pharmacological inhibitors." (PMID 33228783, 2020). "Finally, we defined the expression level of CCR2 among osteosarcoma cell lines and normal osteoblast cell line, which may be associated with migration ability in these cell lines." (PMID 33228783, 2020). "Our data offer a mechanistic explanation for prior reports of the efficacy of MDP in a murine model of osteosarcoma, particularly as the investigators found that MDP was ineffective in Nod2–/– and Ccr2–/– mice." (PMID 39545417, 2024). "Firstly, we referred to two data sets, GSE12865 and GSE14395, and showed that there were high expression levels of four classical M2 macrophages markers, CD163, CCR2, and MRC1, in human osteosarcoma tissue samples." (PMID 35889217, 2022). "A recent study revealed that both CCR2 and CCR4 are highly expressed and involved in patients with osteosarcoma." (PMID 33228783, 2020). "As expected, the positive correlation was found between CCR2 expression level and migration ability among these cell lines, suggesting that CCR2 was closely related to MCP-1-induced osteosarcoma cell metastasis as a key receptor." (PMID 33228783, 2020). "CCR1, CCR2, CCR5, CCR7, CXCR4, CXCR5 and CX3CR1 were found to be expressed in 100% of the osteosarcoma samples tested." (PMID 18215331, 2008). "In osteosarcoma, crucial roles of CCL2 and its receptor CCR2 have been identified." (PMID 40109854, 2025). "To investigate whether HOXA11-AS regulates CCL2 and CCR2, we transfected siHOXA11-AS into PC3 cells and the human osteoblastic osteosarcoma cell line SaOS2." (PMID 33514011, 2021). "In the migration assay, osteosarcoma cell migration was remarkably reduced by the CCR2 inhibitor but not by the CCR4 inhibitor." (PMID 33228783, 2020).
pneumonia (11 papers, 2013 to 2024). An acute, acute and chronic, or chronic inflammation focally or diffusely affecting the lung parenchyma, caused by an infection in one or both of the lungs (by bacteria, viruses, fungi, or mycoplasma.). "Specifically, FOXM1 can affect inflammation in pneumonia through NF-κB and the JAK/STAT signaling pathway and FOXM1 deficiency reduces the expressions of CCL11, CCL24 and chemokine receptors CCR2 and CX3CR1 to further affect inflammation." (PMID 36964598, 2023). "To establish that MyD88 are required for S. pneumoniae induced lung IFNγ, we adoptively transferred (i.n.)WT, STING−/−, or MyD88−/− monocytes to CCR2−/− mice and examined the IFNγ production in the lung by S. pneumonia." (PMID 34512626, 2021). "Furthermore, another study examined the role of CCR2+ monocytes in recruiting neutrophils during pneumonia." (PMID 38596679, 2024). "Thus, successful respiratory infection and pneumonia that occurs during Y. pestis infection requires evasion of early CCR2 responses." (PMID 23633954, 2013). "In addition, the presence of CCR2-bearing blood monocytes enhances neutrophil accumulation, dramatically reflecting the cooperation and coordination between monocytes and neutrophils in leukocyte efflux during pneumonia." (PMID 35327350, 2022). "Increased transcription of chemokine receptors CCR2 (CCL2/monocyte chemoattractant protein-1 (MCP-1) receptor) and CCR5 (CCL3/MIP-1A receptor) were observed, indicating that these inflammatory signals were activated, but receptors XCR1, CCR4, and ACKR3 were downregulated in the pneumonia group." (PMID 36119044, 2022). "We observed that both NK cell depletion and IFN-γ neutralization did not alter bacterial clearance in our WT pneumonia model and that IL-12, independently of its effect on IFN-γ, was able to rescue the delayed bacterial clearance observed in the CCR2-depleted mice." (PMID 39418302, 2024).
psoriasis (11 papers, 2013 to 2026). An autoimmune condition characterized by red, well-delineated plaques with silvery scales that are usually on the extensor surfaces and scalp. "The chemokine receptor CCR2 has been implicated in the pathogenesis of several inflammatory diseases, including psoriasis." (PMID 23472158, 2013). "In human skin, CD2+MHC-II+CCR2+ myeloid precursors were significantly more prevalent in individuals with psoriasis than in healthy control individuals." (PMID 41482544, 2026). "β-Defensin 2, a serum biomarker for psoriasis, is another antimicrobial peptide that is known to induce chemotaxis of immune cells through interaction with CC chemokine receptor 2 (CCR2)." (PMID 30279326, 2018). "CCL2 is expressed at high levels in psoriatic plaques by keratinocytes, suggesting a potential role for CCR2 in psoriasis pathogenesis." (PMID 23472158, 2013). "In this study, we examined the role of the chemokine receptor CCR2 in a murine model of IL-23-induced psoriasis." (PMID 23472158, 2013). "Further, instead of psoriasis-like inflammation seen in WT mice, IL-23-induced cutaneous inflammation in CCR2−/− mice resembled atopic dermatitis." (PMID 23472158, 2013). "The CCR2 ligand CCL2 is expressed by keratinocytes in psoriatic plaques, suggesting a potential role for CCR2 in psoriasis pathogenesis." (PMID 23472158, 2013). "Consequently, there was a significant reduction in the percentage of CD2+MHC-II+CCR2+ myeloid precursors interacting with CD200+ fibroblasts in individuals with PsA compared to in those with psoriasis." (PMID 41482544, 2026). "To further investigate whether inhibiting MDM recruitment could ameliorate psoriasis pathology, we employed a CCR2 antagonist in an IMQ-induced murine psoriasiform dermatitis model." (PMID 40722833, 2025). "To determine the requirement of CCR2 for development of psoriasis, we examined whether CCR2−/− mice are protected from the development of IL-23-induced psoriatic inflammation." (PMID 23472158, 2013). "To test the hypothesis that CCR2 is required for the development of psoriasis, we injected WT and CCR2−/− mice intradermally with IL-23." (PMID 23472158, 2013). "Although injecting IL‐23 might induce atopic dermatitis‐like inflammation rather than psoriasis‐like inflammation in CCR2‐deficient mice, the robust Th1, Th2, Th17 activation, which is similar to human atopic dermatitis, is seen in IL‐23‐injected mice." (PMID 28377495, 2017). "Given this bias toward Th2 immunity in the absence of CCR2 signaling, and a potential role for CCR2 in the pathogenesis of psoriasis, we sought to examine whether CCR2-deficient mice are resistant to the development of IL-23-induced psoriasis." (PMID 23472158, 2013). "Both the CD4+ and CD8+ T cell populations demonstrated attraction to CD2+MHC-II+CCR2+ myeloid precursors in the noninflamed synovia of individuals with psoriasis and the inflamed synovia of individuals with PsA." (PMID 41482544, 2026). "In murine psoriasis, γδ T cells migrate into lesions via CCR2 and CCR6; moreover, they can travel to distal noninflamed skin and LNs to provide memory activation under restimulation." (PMID 35296088, 2022). "Although CCR2 blockade has ameliorated several inflammatory diseases by skewing T cell responses to Th2, intradermal injection of CCR2−/− mice results in an atopic dermatitis-like lesion rather than a psoriasis-like lesion." (PMID 23472158, 2013).
sarcoidosis (11 papers, 2007 to 2024). Sarcoidosis is a multisystemic disorder of unknown cause characterized by the formation of immune granulomas in involved organs. "Moreover, some HLA and CCR5 polymorphisms reduce the risk of sarcoidosis, such as the CCR2-64I polymorphism in the Japanese population." (PMID 37511027, 2023). "The differences between CCR2 polymorphism investigations in sarcoidosis may be explained by linkage disequilibrium between CCR2 gene variants and polymorphisms in a neighboring sarcoidosis susceptibility gene." (PMID 21463523, 2011). "Collectively, these polymorphisms studies combined with the results of our study would suggest that polymorphisms that cause CCR2 dysfunction may lead to a sarcoidosis phenotype that is less severe." (PMID 21463523, 2011). "Some HLA, MHC2TA, BTNL2, CCR2, CCR5, TNF, and ANXA gene polymorphisms are associated with an acute presentation of sarcoidosis—Lofgren’s syndrome, whereas other polymorphisms in these genes are implicated in non-Lofgren’s syndrome." (PMID 37511027, 2023). "This phenotype is characterized by specific genetic associations, like with HLA-DR3, CCR5, and CCR2, that are not all shared with non-LS sarcoidosis." (PMID 35563867, 2022). "Enriched genes including MPO (myeloperoxidase), CXCL11, IL1A, CXCL10, FCGR3B, IL1B, TTN (titin), BATF2, VIP (vasoactive intestinal peptide), TLR3, CCR2, TLR7, and CR1 wereclosely related to sarcoidosis." (PMID 38137330, 2023). "Among chemokine receptors, mRNA expressions of CCR2-var.A (P = 0.018), CCR5 (P = 0.003), CXCR3 (P < 0.001), and CXCR6 (P < 0.001) were elevated in sarcoidosis patients." (PMID 26696750, 2015). "First we studied the relative gene expression of the typical M1 markers, IL-12p35, IL-23p19, CCR7, and M2 markers, IL-10 and CCR2, in total BAL cells of sarcoidosis patients and healthy subjects after culturing in medium for four or 24 h, or after 24 h of LPS stimulation." (PMID 20813038, 2010).
age-related macular degeneration (10 papers, 2010 to 2022). Age-related loss of vision in the central portion of the retina (macula), secondary to retinal degeneration. "Controlling inflammation by suppressing macrophage infiltration and angiogenic ability via the CCR-2/MCP-1 signal may be a useful therapeutic strategy for treating CNV associated with age-related macular degeneration." (PMID 22205983, 2011). "The chemokine receptors CX3CR1 and CCR2 have been implicated in the development of age-related macular degeneration (AMD)." (PMID 25503251, 2014). "In the present study, we evaluated the therapeutic value of INCB3344, a CCR2 antagonist, on a mouse model of age-related macular degeneration and demonstrated that INCB3344 treatment markedly suppressed new CNV formation and shrank established CNVs." (PMID 22205983, 2011). "Ccr2 is involved in age-related macular degeneration as well as aging T-cells." (PMID 31320724, 2019).
Anxiety (10 papers, 2013 to 2025). Intense feelings of nervousness, tension, or panic often arise in response to interpersonal stresses. "Additionally, Wohleb and colleagues showed that anxiety-like behavior associated with repeated social defeat was linked to CCR2-mediated recruitment of peripheral monocytes into the brain." (PMID 25065370, 2014). "Furthermore, a CCR2 antagonist was demonstrated to improve the anxiety-like behavior caused by chronic PS." (PMID 24303068, 2013). "In a recent previous study, CCR2 knockout or antagonism has been shown to reduce stress‐induced anxiety and neuroinflammation, and CCR5 inhibition mitigates anxiogenic responses caused by stress‐induced hippocampal CCR5/CCL5 expression." (PMID 41030589, 2025). "The suggested contribution of MCP-1 to anxiety is also supported by the abolished recruitment of monocytes into the brains of mice under CCR2 blockade." (PMID 39334711, 2024). "Collectively these results confirm the importance of neuronal CCL2 in behavior and highlight the need for further exploration of the CCL2/CCR2 neuronal circuits that exist in brain regions vital to anxiety." (PMID 33192326, 2020). "CCR2 and CCR5 signaling have been implicated in anxiety‐related behaviors." (PMID 41030589, 2025). "Deficiency in CX3CR1 or CCR2, did not affect the increase of Ly6Chi monocytes in the blood after social disruption stress, but prevented brain infiltration of CD45hi CD11b+ macrophages and the development of stress-induced anxiety." (PMID 30057531, 2018). "As such monocyte mobilization depends on CCR2 activation, we suggest that high systemic sCD14 and MCP-1 levels could reflect the mobilization of monocytes into the bloodstream of patients with anxiety." (PMID 39334711, 2024). "While upregulation of CCR2 in the AMG associated with neuropathic pain has not previously been reported, an overexpression of CCL2 in the CeA of mice with partial sciatic nerve ligation (PSNL) that exhibited anxiety-like behavior and hypersensitivity to mechanical stimuli has been demonstrated." (PMID 40244217, 2025). "Moreover, administration of CC chemokine receptor 2 (CCR2) inhibitor that blocked the monocyte chemotactic activity, substantially attenuated the anxiety-like behaviors in the highly myopic mice in OFT and EPM, suggesting a key role of the infiltrated monocytes in the high myopia-related anxiety." (PMID 37699875, 2023).